GDF11 (growth differentiation factor 11)
Diseases named in the same sentence as GDF11 in open-access papers (continued):
Sharing a sentence is not in itself a finding about the gene and the disease.
myocardial infarction (13 papers, 2018 to 2025). Gross necrosis of the myocardium, as a result of interruption of the blood supply to the area, as in coronary thrombosis. "Here, we aimed to probe the role of GDF11 in acute myocardial infarction (MI), a frequent cause of heart failure and premature death during ageing." (PMID 37742057, 2023). "Our results indicated that pretreatment with GDF11 remarkably improved cardiac function and reduced post-ischemia myocardial infarct size, which may be implicated in antioxidant stress and up-regulating autophagy level in diabetic myocardium." (PMID 31939595, 2020). "In a clinical study, TERT up‐regulation facilitated growth differentiation factor 11 (GDF11)‐mediated restoration of VEGFR2+/CD133+ cells isolated from older adult patients who had suffered myocardial infarctions via eNOS and SMAD 2/3 signalling." (PMID 37041671, 2023). "In addition, increasing the GDF11 level has cardioprotective effects in myocardial infarction and ischemic reperfusion injury, as well as in a myocardial pressure overload model." (PMID 34262905, 2021). "This novel role of GDF11 may be used for a new approach of stem cell therapy for myocardial infarction." (PMID 32515551, 2020). "A question we asked ourselves was whether GDF11 could produce cardioprotective effects in the setting of acute myocardial infarction." (PMID 33100331, 2020). "Moreover, GDF11 levels were particularly elevated in those at high risk for adverse outcomes following the acute event, with circulating GDF11 emerging as an independent predictor of myocardial infarct size, as estimated by standardized peak creatine kinase-MB levels." (PMID 37742057, 2023). "To further explore whether GDF11 plays an important role in adjusting cardiomyocytes pyroptosis in myocardial infarction, we evaluated the protein levels of NLRP3, ASC, cleaved-caspase-l (c-caspase-1), and GSDMD-N in ischemic heart and hypoxia cardiomyocytes with or without GDF11 treatment." (PMID 33100331, 2020). "HOXA3 is upregulated by growth differentiation factor 11 (GDF11) and mediates inhibition of cardiomyocyte pyroptosis following myocardial infarction." (PMID 41181801, 2025). "Furthermore, recent findings highlight the detrimental impactof persistently elevated growth differentiation factor 11 (GDF11) levels duringaging, which may contribute to the loss of cardioprotective mechanisms andpoor outcomes in elderly patients following acute myocardial infarction." (PMID 40776966, 2025). "Unexpectedly, boosting systemic Gdf11 by recombinant GDF11 delivery (0.1 mg/kg body weight over 30 days) prior to myocardial I/R augmented myocardial infarct size in C57BL/6 mice irrespective of their age, predominantly by accelerating pro-apoptotic signalling." (PMID 37742057, 2023).
Obesity (13 papers, 2018 to 2026). Accumulation of substantial excess body fat. "To investigate the underlying mechanisms of GDF11 activity in preventing obesity and obesity-related complications, we also assessed the mRNA level of selected genes involved in glucose and lipid metabolism in the liver." (PMID 31847906, 2019). "Overexpression of the Gdf11 gene prevents the manifestations of obesity and T2D in mice, including HFD-induced weight gain, hyperglycemia, insulin resistance, and glucose intolerance." (PMID 39872377, 2024). "The promising effects of GDF11 analogues on metabolic disorders (such as obesity and T2D) and liver diseases like NAFLD, liver fibrosis, and HCC are still in early preclinical stages." (PMID 38494851, 2024). "Another possibility was that GDF11 reduced metabolic disorders by decreasing inflammation, which is responsible for many metabolic complications such as obesity." (PMID 38494851, 2024). "Collectively, we demonstrated that GDF11 is a potential target for inhibiting adipogenic differentiation and combating obesity." (PMID 36755591, 2023). "Our study clarified the effects and regulatory mechanisms of GDF11 on adipogenic differentiation and demonstrated that GDF11 is a potential target for inhibiting adipogenic differentiation and combating obesity." (PMID 36755591, 2023). "In this work, we aimed to clarify the effects and regulatory mechanism of GDF11 on adipogenic differentiation and helped to evaluate the translational potential of GDF11 against obesity." (PMID 36755591, 2023). "Further studies are essential for the development of GDF11‐ and other metabotrophins‐based systemic therapies for obesity and related cardio‐ and neurometabolic diseases, including Alzheimer's disease." (PMID 35920128, 2022). "Since GDF11 administration can ameliorate high fat induced obesity, we sought to test its in vivo effect in micegenetic obesity model, ob/ob mice." (PMID 35920128, 2022). "As systemic GDF11 treatment can improve glucose homeostasis and insulin sensitivity in rodent obesity models, we tested internalization/uptake of 2‐deoxy glucose in mature 3T3‐L1 adipocytes after GDF11 treatment." (PMID 35920128, 2022). "Since the expansion of WAT mass seen in obesity involves hyperplasia, hypertrophy, inflammation, and glucose turnover in adipocytes, the beneficial effects of GDF11 therapy in obesity are likely to occur at multiple levels." (PMID 35920128, 2022). "We show evidence that link GDF11 to adipogenic differentiation, glucose, and insulin homeostasis, which are pointing towards potential beneficial effects of GDF11‐based “anti‐obesity” therapy." (PMID 35920128, 2022). "Recently, it was reported that Gdf11 gene transfer or recombinant GDF11 protein supplementation in rodents ameliorated high‐fat diet (HFD) induced obesity, hyperglycemia, insulin resistance, nonalcoholic fatty liver disease (NAFLD) and obesity." (PMID 35920128, 2022). "Recently, research efforts presented GDF11 as an important circulating MTF that significantly ameliorates high-fat diet-induced obesity, hyperglycemia, insulin resistance and liver steatosis by reducing body weight and improving glucose homeostasis." (PMID 33923652, 2021). "Early reports showed that patients with type 2 diabetes or obesity exhibited higher circulating levels of GDF11, while others showed that circulating GDF11 levels were unaffected by the presence of obesity or type 2 diabetes." (PMID 33886503, 2021). "Altogether, these findings demonstrate that GDF11 administration triggers the development of liver fibrosis in an obesity-dependent NAFLD background." (PMID 33126224, 2020). "Gdf11 gene transfer alleviates HFD-induced obesity, hyperglycemia, insulin resistance, and fatty liver development." (PMID 31847906, 2019). "Some reports showed that the circulation level of GDF11 increased in type 2 diabetes (T2D) or obesity in humans and mice." (PMID 31847906, 2019).
Obesity (continued). "The focus of the current study is to investigate the functions of GDF11 in regulating metabolic homeostasis and energy balance in high fat diet-induced obesity mice and animals with STZ-induced diabetes." (PMID 31847906, 2019). "Hydrodynamic injection of Gdf11 gene generated the sustained blood circulating level of GDF11 and long-term anti-diabetic effects, indicating that GDF11 has therapeutic potential in treating diabetes and obesity-related metabolic diseases." (PMID 31847906, 2019). "As inflammation is known for its role in inducing obesity and metabolic complications, the anti-inflammation function of GDF11 is likely one of the reasons for the beneficial effects seen in animals employed in our study." (PMID 31847906, 2019). "In this study, we demonstrate that hydrodynamic transfer of Gdf11 gene prevented HFD induced obesity, hyperglycemia, insulin resistance and fatty liver in mice." (PMID 31847906, 2019). "High fat diet (HFD)-induced obesity was employed to examine the impacts of Gdf11 gene transfer on HFD-induced adiposity, hyperglycemia, insulin resistance, and hepatic lipid accumulation." (PMID 31847906, 2019). "In summary, we demonstrate that Gdf11 gene transfer alleviated HFD-induced obesity, hyperglycemia, insulin resistance and fatty liver development in mice." (PMID 31847906, 2019). "Moreover, the potential therapeutic effects of GDF11 on metabolic disorders such as obesity, T2D, glucose and insulin homeostasis dysregulation, and energy imbalance were recently evaluated." (PMID 38494851, 2024). "Conversely, other researchers found that circulating GDF11 remains unchanged in T2D and obesity." (PMID 39872377, 2024). "Recently, studies on the relationship between GDF11 and obesity have increased greatly." (PMID 36755591, 2023). "Many studies have explored the relationships of GDF11 with obesity and diabetes." (PMID 33886503, 2021). "Notably, GDF11 has been used to treat metabolic diseases, including obesity, insulin resistance, fatty liver development, and hyperglycemia." (PMID 33886503, 2021). "Leptin might thus be required for GDF11-induced adiponectin secretion during obesity, and a significant correlation between circulating GDF11 and leptin levels has been found in obese patients." (PMID 33126224, 2020). "However, little is known about the function of GDF11 in the development of obesity and obesity-related metabolic disorders." (PMID 31847906, 2019). "However, the detailed mechanisms of GDF11 in preventing obesity and fatty liver remain elusive, as well as the mechanisms of GDF11 in regulating oxygen consumption, thermogenesis, and inflammation." (PMID 31847906, 2019). "This is to our knowledge the first study analyzing the levels of GDF11 in obesity." (PMID 30897065, 2019). "Serum GDF11 concentrations in humans decrease in older ages being unaltered in obesity and T2D." (PMID 30897065, 2019). "These suggest that GDF11-mediated thermogenesis and energy consumption play important roles in prevention of HFD-induced obesity and metabolic disorders." (PMID 31847906, 2019). "Also, GDF11 activated multiple signal pathways, such as Smad, Akt, and p38 MAPK, which were involved in the development of obesity, fatty liver, and insulin resistant, implying that GDF11 may play an important role in obesity and obesity-related metabolic disorders." (PMID 31847906, 2019). "Beneficial effects of Gdf11 gene transfer in preventing HFD-induced obesity and metabolic disorders such as glycemia, insulin resistance, and fatty liver have prompted us to explore its effects on animals with obesity." (PMID 31847906, 2019). "Relatively large variability in the EPS‐induced response (GDF11, IL8 mRNA) could be, to an extent, attributable to the interindividual differences in the clinical phenotypes of the cells' donors, including family history of obesity and type 2 diabetes." (PMID 40923494, 2026).
Obesity (continued). "In addition, GDF11 participates in the regulation of many obesity-related signaling pathways, including SMAD, AKT, and p38 MAPK, indicating its importance in metabolism-related diseases, such as obesity, fatty liver, and T2D." (PMID 39872377, 2024). "Therefore, GDF11 increased thermogenesis, energy expenditure, and regulated glucose and lipid metabolism through TGF‐β/SMAD2, PI3K/AKT/FoxO1 and AMPK pathways, which might eventually lead to the prevention of obesity and other metabolic disorders." (PMID 38494851, 2024).
Cachexia (12 papers, 2017 to 2025). Severe weight loss, wasting of muscle, loss of appetite, and general debility related to a chronic disease. "In cardiac muscle, increased circulating GDF11 levels have been associated with cardiac atrophy and cachexia." (PMID 40558549, 2025). "Since it was previously reported that supraphysiologic overexpression of GDF11 in the liver of young mice induced weight loss and cachexia through activation of GDF15 and anorexia, we sought to examine this in our paradigm of systemic rGDF11 administration." (PMID 31637864, 2020). "Fourth, young blood’s components may instead exacerbate the progression of the disease, such as high levels of GDF11 cause severe cachexia, death, cardiac and skeletal muscle wasting, TNF-α and IL-6 promote cardiac remodeling and inflammation generation." (PMID 40969375, 2025). "Additionally, we analyzed fold-changes of GDF11 which is well known for its rejuvenating effect but also associated with cachexia, partially through upregulation of GDF1519." (PMID 37495707, 2023). "However, mice receiving high doses of GDF11 (5 mg/kg) developed cachexia and premature death, showing that excessively high doses of GDF11 can cause deleterious effects at high doses, as others have confirmed." (PMID 38235060, 2023). "Studies indicate GDF11 mediates beneficial roles in cardiac tissues and detrimental effects in skeletal muscle; however, we also need to note that a high level of GDF11 (5.0 mg/kg) caused severe body weight loss, cachexia, and death." (PMID 35012677, 2022). "Juli E. Jones recently demonstrated that elevated GDF11 induces cachexia in mice, reducing muscle mass, food intake and body weight while upregulating plasma GDF15." (PMID 40969368, 2025). "The interplay of GDF11 and GDF15 in cachexia and the potential effects of GDF11 induction by BET inhibition in that context still remain to be further elucidated." (PMID 37495707, 2023). "The GDF11 group began exhibiting signs of severe cachexia beginning at day 14, and the study was terminated following the death of a mouse at day 16 (21% loss of initial body mass by the group)." (PMID 28270449, 2017). "Moreover, other reports have indicated that GDF11 induces cachexia, produces deleterious effects on muscular regeneration, and decreases satellite cell expansion in old mice." (PMID 29783655, 2018).
diabetes (10 papers, 2017 to 2025). "Elevated circulating GDF11 levels increased prevalance of diabetes, prior cardiac abnormalities, frailty, risk of post-operative complications and re-hospitalization." (PMID 29113418, 2017). "Therefore, according to our evidence, GDF11 shows potential as a novel therapy for reducing the vulnerability of MIR in diabetes, while, further studies are needed to explore the underlying molecular mechanisms." (PMID 31939595, 2020). "However, whether GDF11 could confer protective effects to MIR in diabetes, and its underling mechanisms are still unclear." (PMID 31939595, 2020). "Taken together, our study reveals that GDF11 overexpression protects against diabetes-induced myocardial injury by attenuating cardiac fibrosis, oxidative stress, and cardiomyocyte apoptosis by activating the SIRT1 signaling pathway." (PMID 34262905, 2021). "Here, we confirmed a novel molecular target for DCM by which GDF11 attenuated cardiac dysfunction and reversed adverse myocardial remodeling in diabetes." (PMID 34262905, 2021). "Pretreatment with GDF11 significantly improved cardiac morphology and function in diabetes, concomitant with decreased arrhythmia severity, infarct size, CK-MB, LDH and 15-F2tisoprostane release, increased SOD activity and autophagy level." (PMID 31939595, 2020). "Contrary to our results, another report showed that increased circulating GDF11 was detected in a greater proportion of subjects with diabetes." (PMID 30897065, 2019). "More recent studies have suggested the potential of GDF11 for the treatment of metabolic diseases such as atherosclerosis, type 2 diabetes, and diabetes-related vascular dysfunctions." (PMID 31847906, 2019). "GDF11 can also directly and effectively block the development of diabetes." (PMID 38715043, 2024). "After establishing a mouse model of diabetes by administering a high-fat diet and streptozotocin, intramyocardial injection of an adeno-associated virus was used to achieve myocardium-specific GDF11 overexpression." (PMID 34262905, 2021). "Effects of GDF11 on arrhythmias and mortality in diabetes induced by myocardial IR injury." (PMID 31939595, 2020). "We hypothesized that treatment with exogenous recombination of GDF11 could efficiently reduce MIR injury in diabetes and enable us to systematically explore its cardioprotective mechanisms." (PMID 31939595, 2020). "In addition, there are contradictory reports regarding the role of GDF11 in aging, cardiovascular disease, diabetes mellitus, osteogenesis, skeletal muscle development, and neurogenesis." (PMID 29113418, 2017). "Additionally, there are contradictory reports regarding GDF11 function in cardiovascular disease, diabetes mellitus, osteogenesis, skeletal muscle development and neurogenesis." (PMID 29113418, 2017). "Therefore, there are contradictory views on the role of GDF11 in the field of aging, cardiovascular diseases, diabetes, muscle dysfunction and endothelial cell function." (PMID 29113418, 2017). "Therefore, in this review, we describe the GDF11 signaling pathway and its role in development, erythropoiesis, aging, cardiovascular disease, diabetes mellitus, cancer and other diseases." (PMID 29113418, 2017). "Since its discovery in 1999, studies have shown the involvement of GDF11 in normal physiological processes, such as embryonic development and erythropoiesis, as well as in the pathophysiology of aging, cardiovascular disease, diabetes mellitus, and cancer." (PMID 29113418, 2017). "Furthermore, GDF11 inhibited the diabetes-induced upregulation of the pro-oxidant gp91phox." (PMID 34262905, 2021). "Similarly, GDF11 has a dual role in diabetes and cardiovascular diseases." (PMID 29113418, 2017). "After a week, we overexpressed GDF11 by weekly intravenous injection of AAV9-GDF11 to generate mice GDF11 overexpression and diabetic DCM." (PMID 38715043, 2024).
diabetes (continued). "To evaluate the role of the GDF11 protein in DCM, we successfully induced diabetes in mice using STZ injection for three consecutive days." (PMID 38715043, 2024). "Our results indicate that the cardiac-specific overexpression of GDF11 can improve DCM symptoms by reducing myocardial cell death and fibrosis, which is consistent with its function in promoting angiogenesis in diabetes." (PMID 38715043, 2024). "The SIRT1 inhibitor also blunted the decrease in cardiomyocyte apoptosis after GDF11 overexpression, as well as the changes in apoptotic proteins induced by AAV-GDF11 in diabetes." (PMID 34262905, 2021). "Gdf11 gene transfer also improved metabolic homeostasis in obese mice and mice with STZ-induced diabetes." (PMID 31847906, 2019). "GDF11 also improves glucose homeostasis in obese mice and mice with STZ-induced diabetes." (PMID 31847906, 2019). "We demonstrate that GDF11 overexpression via gene transfer leads to significant improvement of metabolic homeostasis in obese mice and mice with STZ-induced diabetes, and blockade of high fat diet-induced weight gain, hyperglycemia, insulin resistance, and fatty liver development." (PMID 31847906, 2019).